LRBA (LPS responsive beige-like anchor protein)
Diseases named in the same sentence as LRBA in open-access papers (continued):
Sharing a sentence is not in itself a finding about the gene and the disease.
breast tumor (1 paper, 2013). "LRBA was found upregulated in several different cancers including ER + breast tumor, and LRBA knockdown promotes cancer cell apoptosis." (PMID 23496902, 2013).
deficiency (1 paper, 2021). "LRBA mutations also result in hypogammaglobulinaemia and B cell deficiencies." (PMID 35154081, 2021).
Failure to thrive (1 paper, 2020). Failure to thrive (FTT) refers to a child whose physical growth is substantially below the norm. "Classical clinical manifestations of LRBA deficiency was evident in our patient including chronic diarrhea, failure to thrive, and interstitial pneumonia." (PMID 32154999, 2020).
gastric atrophy (1 paper, 2025). "This case elucidates a distinct and severe phenotype form of atrophic gastritis caused by the c.229_230del; p.Gln77Valfs*2 homozygous mutation in LRBA, expanding the clinical spectrum of LRBA deficiency." (PMID 41378195, 2025).
idiopathic thrombocytopenic purpura (1 paper, 2021). "One patient diagnosed with JDH met both the ACR/EULAR-2019 and the SLICC-2012 criteria, and one patient with LPS-responsive beige-like anchor protein (LRBA) gene mutation with idiopathic thrombocytopenic purpura and hypogammaglobulinaemia met the SLICC-2012 classification criteria." (PMID 33690793, 2021).
Leukoencephalopathy (1 paper, 2024). This term describes abnormality of the white matter of the cerebrum resulting from damage to the myelin sheaths of nerve cells. "Posttransplant leukoencephalopathy was diagnosed, likely due to the process of transplantation itself, but it cannot be ruled out that this was a step related to LRBA deficiency." (PMID 39108694, 2024).
myocardial infarction (1 paper, 2020). Gross necrosis of the myocardium, as a result of interruption of the blood supply to the area, as in coronary thrombosis. "The expression of LRBA is decreased 2 d after myocardial infarction." (PMID 33062700, 2020).
T-cell deficiency (1 paper, 2017). "LRBA serves as a key regulator in T-cell function, and mutation in LRBA could cause T-cell deficiency and immune dysregulation." (PMID 28953250, 2017).
Vici syndrome (1 paper, 2024). A very rare and severe congenital multisystem disorder characterized by the principal features of agenesis of the corpus callosum, cataracts, oculocutaneous hypopigmentation, cardiomyopathy and combined immunodeficiency. "Other patients with mutations in autophagy-related genes (e.g LRBA, TTP2 and EPG5 in Vici syndrome) show variable immune system abnormalities." (PMID 37614038, 2024).
cancer (8 papers, 2012 to 2024). A tumor composed of atypical neoplastic, often pleomorphic cells that invade other tissues. "The possible role of LRBA gene knockout in cancer development and its prognosis remains to be elucidated." (PMID 28720148, 2017). "Pedigree studies based on the UPDB have previously provided the identification of BRCA1 and BRCA2, and more recently have identified additional rare cancer predisposition variants (GOLM1; CELF4; FANCM; ERF; LRBA; FGF5) in similar sets of sampled high-risk pedigrees." (PMID 38136396, 2023). "LRBA is found to be overexpressed in several different types of cancers and could be involved in cell proliferation and apoptosis." (PMID 35397606, 2022). "The role of LRBA gene knockout in cancer development and its prognosis remains to be elucidated." (PMID 28720148, 2017). "LRBA interacts with multiple important signal transduction pathways including EGFR and its deregulation in several cancer types has been shown to facilitate cancer cell growth." (PMID 28650955, 2017). "Inhibition of LRBA function may repress cancer cell growth in many cancer cell lines, but not all." (PMID 28720148, 2017).
genetic disorder (4 papers, 2021 to 2026). "Lipopolysaccharide-responsive and beige-like anchor protein (LRBA) deficiency is a rare genetic disorder characterized by immune dysregulation." (PMID 42048445, 2026).
tumor (4 papers, 2013 to 2024). "Among them, TAZ was up-regulated in tumor tissue compared with para-cancerous tissue, and the expression of the remaining eight genes (including SLC25A4, SLC25A5, PARK, PINK1, MFN2, HUWE1, VPS13D, and LRBA) was down-regulated in tumor tissue." (PMID 38373978, 2024).
infection (3 papers, 2019 to 2024). The state of being infected such as from the introduction of a foreign agent such as serum, vaccine, antigenic substance or organism. "Expression of LRBA was downregulated at a later time post-infection in all three lines." (PMID 31533607, 2019). "These are involved in smooth-muscle function (FGFR1, GATA5 and STIM1), tissue organization (ADAMTS10), alveolar and epithelial function (ABCA3 and CLDN18), and inflammation and immune response to infection (CFH, CYTL1, HMCN1, LRBA and STIM1)." (PMID 36914875, 2023).
metabolic disorders (1 paper, 2025). "These additional putative mono/oligogenic SLE genes are involved in type I IFN regulation (DDX58, NLRC4 and PACSIN1), disruption of B cell and T cell tolerance (DOCK8, FAS and LRBA) and metabolic disorders (CYBB, MAN2B1, SLC7A7)." (PMID 40386946, 2025).
neurological diseases (1 paper, 2023). "Although LRBA is not well studied, 25% of patients with LRBA deficiency are documented to display neurological diseases." (PMID 37998360, 2023).
LRBA also shares sentences with these, for which no sentence is quoted: polyendocrinopathy (5 papers); autoimmune enteropathy (2); chronic granulomatous disease (2); hypothyroidism (2); lymphoproliferative disorders (2); polyarthritis (2); X-linked lymphoproliferative syndrome (2); asthma (1); autoimmune hemolytic anemia (1); Autoimmune polyendocrinopathy-candidiasis-ectodermal dystrophy (1); autoimmune thyroid disease (1); Bloom syndrome (1); bronchiectasis (1); Burkitt lymphoma (1); celiac disease (1); Chediak-Higashi syndrome (1); Chronic diarrhea (1); combined immunodeficiencies (1); combined immunodeficiency (1); COVID-19 (1); Crohn disease (1); deafness (1); dysgammaglobulinemia (1); eosinophilia (1); FADD deficiency (1); familial Mediterranean fever (1); gastric adenocarcinoma (1); gastropathy (1); glycogen storage disease type 1b (1); hemophagocytic lymphohistiocytosis (1).
A further 19 diseases each share a sentence with LRBA in 1 paper.